GRINA (glutamate ionotropic receptor NMDA type subunit associated protein 1)
Description:
Potential apoptotic regulator.
Synonyms: LFG1; NMDARA1; TMBIM3; HNRGW
Tractability: Antibody: UniProt predicts a signal peptide or a membrane-spanning region. PROTAC: ubiquitination databases record sites on it.
Gene: Protein-coding gene on chromosome 8 (143,990,053 to 143,993,427, forward strand). Ensembl gene ENSG00000178719.
Subcellular location: Membrane
Subcellular location (Human Protein Atlas): Nucleoli fibrillar center; Cytosol
Gene Ontology:
Molecular function: protein binding; calcium channel activity; transmembrane transporter binding
Biological process: negative regulation of extrinsic apoptotic signaling pathway via death domain receptors; negative regulation of neuron apoptotic process; calcium ion transmembrane transport
Cellular component: Golgi membrane; endoplasmic reticulum membrane; Golgi apparatus; endoplasmic reticulum; membrane
Genetic constraint (gnomAD): Loss-of-function variants: 19 observed, 32.42 expected, observed/expected ratio (o/e) 0.59, 90% interval 0.41 to 0.86. The upper end of that interval is the gene's LOEUF score, 0.86, which puts it in group 3 of 6, group 1 being the genes least tolerant of losing a copy. Missense variants: 305 observed, 365.71 expected, observed/expected ratio (o/e) 0.83, 90% interval 0.76 to 0.92. Synonymous variants: 190 observed, 158.52 expected, observed/expected ratio (o/e) 1.2, 90% interval 1.06 to 1.35.
Homologues: Orthologues: chimpanzee GRINA (99% identical), rabbit GRINA (93% identical), guinea pig GRINA (90% identical), rat Grina (88% identical), mouse Grina (87% identical), macaque GRINA (78% identical), pig GRINA (75% identical), zebrafish grinaa (64% identical), Drosophila melanogaster Nmda1 (34% identical), Drosophila melanogaster Lfg (30% identical), Drosophila melanogaster CG30379 (28% identical), Drosophila melanogaster Recs1 (25% identical), and 3 more. Paralogues in human: FAIM2 (35% identical), TMBIM1 (34% identical), TMBIM4 (22% identical), GHITM (15% identical), TMBIM6 (10% identical).
Diseases named in the same sentence as GRINA in open-access papers:
GRINA is named in the same sentence as 26 diseases in open-access papers, as found by Europe PMC text mining. Sharing a sentence is not in itself a finding about the gene and the disease. The quoted sentences say what the papers report.
gastric cancer (6 papers, 2012 to 2022). A primary or metastatic malignant neoplasm involving the stomach. "In the following work, we probed the molecular mechanisms underlying GRINA mediated gastric cancer tumorigenesis." (PMID 30541591, 2018). "First, we explored the cause of elevated GRINA expression in gastric cancer." (PMID 30541591, 2018). "Recent clinical research has demonstrated that the transmembrane protein GRINA modulates aerobic glycolysis and promotes tumor progression in gastric cancer." (PMID 36570009, 2022). "A recent article confirmed that GRINA is upregulated in gastric cancer and that its regulation is mediated by c-Myc." (PMID 31426446, 2019). "The apoptosis rate was significantly increased in gastric cancer cell lines after knockdown of GRINA." (PMID 30541591, 2018). "In this study, we analysed GRINA expression in several databases and found that it was significantly elevated in gastric cancer tissues." (PMID 30541591, 2018). "IHC staining on TMAs containing 569 gastric cancer samples was performed and the results showed that GRINA expression was significantly correlated with clinicopathological parameters such as classification, TNM stages, lymphatic metastasis, and so on." (PMID 30541591, 2018). "Our study also demonstrates the oncogenic activities of GRINA in gastric cancer cells under metabolic stress." (PMID 30541591, 2018). "In our work, GRINA knockdown in gastric cancer cells promoted cell apoptosis, and induced downregulation of Bcl-2 and upregulation of Bax, which indicates that GRINA inhibits apoptosis through Bcl-2 family members." (PMID 30541591, 2018). "We also explored the molecular mechanism of GRINA upregulation and its function in gastric cancer development and progression." (PMID 30541591, 2018). "In the KM-plotter database we found that high GRINA expression indicated a poor prognosis in gastric cancer." (PMID 30541591, 2018). "Human gastric cancers have increased levels of GRINA, which promotes growth of gastric cancer and inhibits tumor cells apoptosis." (PMID 30541591, 2018). "The mRNA levels of GRINA in 7 gastric cancer cell lines (SGC-7901, MGC-803, BGC-823, MKN45, HGC27, AGS, N87) and in a normal immortalized gastric mucosal epithelial cell line (GES-1) were examined by Real-time PCR." (PMID 30541591, 2018). "A correlation analysis based on 420 gastric cancer samples in TCGA database showed that c-Myc was highly correlated with GRINA expression." (PMID 30541591, 2018). "The expression of GRINA is upregulated in breast cancer, colorectal cancer and gastric cancer." (PMID 31426446, 2019). "GRINA promoted the proliferation, migration and invasion capacity of gastric cancer cells." (PMID 30541591, 2018). "Being a membrane protein structurally similar to TMBIM6, whether GRINA influences gastric cancer cell apoptosis by regulating Bcl-2 family members remains to be verified." (PMID 30541591, 2018). "We inferred that GRINA upregulation in gastric cancer was mainly induced by transcription factors." (PMID 30541591, 2018). "To further understand the mechanism by which GRINA promoted gastric cancer cell proliferation, we added 1 mM thymidine to each cell group for 24 h and cultured the cells in RPMI 1640 medium without FBS for another 24 h, and then counted the proportion of cells in each cell cycle phase." (PMID 30541591, 2018). "GRINA promoted gastric cancer cell proliferation, migration, and invasion." (PMID 30541591, 2018). "We then assessed GRINA expression in gastric cancer cell lines and tissues." (PMID 30541591, 2018). "We next studied the biological function of GRINA in gastric cancer progression." (PMID 30541591, 2018). "We found higher expression of GRINA in the 7 gastric cancer cell lines than in GES-1." (PMID 30541591, 2018).
gastric cancer (continued). "The results of GSEA using TCGA database also showed striking alterations in metabolic processes including upregulation of glycolysis and reactive oxygen species pathways, which indicated a correlation between GRINA expression and enhanced glycolytic metabolism in gastric cancer." (PMID 30541591, 2018). "Analysis of 876 gastric cancer patients with 33 months of follow-up data in KMplotter database demonstrated that patients with high GRINA expression had worse overall survival (OS) than those with low GRINA expression, suggesting that GRINA indicates poor prognosis in gastric cancer." (PMID 30541591, 2018). "GRINA knockdown decreased PI3K/Akt/mTOR signaling and glycolytic metabolism in gastric cancer cells." (PMID 30541591, 2018). "In samples from TCGA database and Gene Expression Omnibus (GEO) database, GRINA expression was found to be significantly increased in gastric cancer samples compared with that in normal samples (matched or not matched)." (PMID 30541591, 2018). "The results showed that silencing of GRINA attenuated whereas overexpression of GRINA enhanced the glycolytic capability of gastric cancer cells but not oxidative phosphorylation, indicating that GRINA principally affects the glycolytic component of glucose metabolism." (PMID 30541591, 2018). "Early research demonstrated that GRINA knockdown in AGS and BGC-823 cell lines resulted in downregulation of Bcl-2 and Bcl-xl but upregulation of Bax and Bak, which suggest that GRINA could regulate gastric cancer cell apoptosis through Bcl-2 family members." (PMID 30541591, 2018).
major depression (3 papers, 2009 to 2023). "Upregulation of GRINA transcripts was observed in post-mortem brains of patients with major depressive disorder, supporting a role in brain functions." (PMID 37672513, 2023). "In addition, gene expression of TMBIM3/GRINA is dysregulated in brains of patients with major depression and in various cancers." (PMID 31683519, 2019).
celiac disease (2 papers, 2019 to 2021). An autoimmune genetic disorder with an unknown pattern of inheritance that primarily affects the digestive tract. "The authors suggested that 33-mer gliadin molecule is a natural antagonist interfering with the normal interactions of GRINA, thus impacting the extraintestinal manifestations of celiac disease." (PMID 34063062, 2021). "Here we dissect, with the help of different software tools, the potential roles of GRINA in the cell and how they may be altered in diseases, such as schizophrenia or celiac disease." (PMID 31426446, 2019).
schizophrenia (2 papers, 2008 to 2019). A major psychotic disorder characterized by abnormalities in the perception or expression of reality. "However, alternative promoter usage and significantly lower expression of GRINA was detected in postmortem superior temporal gyrus of schizophrenia patients in contrast to non-psychiatric controls." (PMID 31426446, 2019).
agnosia (1 paper, 2023). A rare disorder characterized by the lack of ability to recognize individuals, objects, shapes, sounds, or smells. "Since it is likely that effects on higher order visual perception will not be evident in mice, GRINA remains a potentially interesting candidate gene for consideration of a role in developmental colour agnosia." (PMID 37672513, 2023).
Alzheimer disease (1 paper, 2022). A progressive, neurodegenerative disease characterized by loss of function and death of nerve cells in several areas of the brain leading to loss of cognitive function such as memory and language. "In recent research, hypoxia-induced miR-210 was shown to target synaptic function genes (GRINA, TMUB1, and AP2S1), plasticity genes (ACTB), Alzheimer’s disease genes (APOE), and genes implicated in MAPK/VEGF and OXPHOS signaling pathways." (PMID 35626359, 2022).
amyloid (1 paper, 2023). "Finally, GRINA encodes an NMDA receptor subunit, dysregulation of which has been linked to AD via calcium signalling alterations, as well as activation of NMDA receptors resulting in amyloid-induced mitochondrial toxicity and neuronal dysfunction when this activation is mediated by amyloid." (PMID 37438770, 2023).
Cerebral ischemia (1 paper, 2019). Restriction of arterial blood supply to the brain associated with insufficient oxygenation to support the metabolic requirements of the tissue. "We have recently demonstrated that GRINA-deficiency increased infarct volumes after murine cerebral ischemia and enhanced apoptosis rates in neurons after oxygen–glucose deprivation (OGD)." (PMID 31683519, 2019). "GRINA confers neuroprotection and is regulated by erythropoietin (EPO) after murine cerebral ischemia." (PMID 31683519, 2019).
dyslipidemia (1 paper, 2022). "The study also demonstrated that DNA methylation of three CpG sites in the GRINA gene was associated with dyslipidemia." (PMID 36570009, 2022). "The methylation levels of GRINA are a risk factor for dyslipidemia (P = 0.019, OR = 1.548 95% CI [1.073–2.233])." (PMID 36570009, 2022). "One of the most significant advantages is that it is the first to discover that GRINA methylation is associated with dyslipidemia." (PMID 36570009, 2022). "The findings of this study reveal that the DNA methylation of GRINA increases the risk for dyslipidemia in humans." (PMID 36570009, 2022). "The results of this study suggest that DNA methylation of GRINA increases the risk for dyslipidemia in humans." (PMID 36570009, 2022). "DNA methylation of GRINA, on the other hand, was associated with dyslipidemia." (PMID 36570009, 2022). "Dyslipidemia is linked to CpG sites 34 and 69 of the GRINA gene." (PMID 36570009, 2022). "Logistic regression analysis revealed that DNA methylation of GRINA may increase the risk of dyslipidemia." (PMID 36570009, 2022). "Participants with higher GRINA methylation have a 54% increased risk of dyslipidemia." (PMID 36570009, 2022). "This study also discovered that several GRINA haplotypes are associated with dyslipidemia." (PMID 36570009, 2022). "When compared with the control group, the dyslipidemia group had significantly higher levels of methylation in the GRINA gene (2.68 vs 2.36, P = 0.04)." (PMID 36570009, 2022). "This study found a significant correlation between DNA methylation in the CpG region of GRINA and dyslipidemia." (PMID 36570009, 2022). "When compared with the control group, the dyslipidemia group had higher DNA methylation levels of GRINA (2.71 vs 2.44, P = 0.04)." (PMID 36570009, 2022). "Further functional research is required to interpret the mechanisms linking GRINA methylation to dyslipidemia." (PMID 36570009, 2022). "In a recent GWAS study, the GRINA gene has been reported to be associated with dyslipidemia, but its molecular mechanism has not been thoroughly investigated." (PMID 36570009, 2022).
femoral neck fracture (1 paper, 2019). Fractures of the short, constricted portion of the thigh bone between the femur head and the trochanters. "Our AEI data indicate that the OA risk–conferring A allele of rs11780978 correlates with reduced expression of PLEC but with increased expression of GRINA, while our RNA‐Seq data revealed increased PLEC expression but decreased GRINA expression, in OA versus non‐OA (femoral neck fracture) cartilage." (PMID 30730609, 2019).
infarction (1 paper, 2019). A localised pathological necrosis of tissue resulting from obstruction of the blood supply usually by a thrombus, an embolus, or vascular torsion. "Our findings indicate a crucial role for GRINA in both the development and progression of infarction." (PMID 31683519, 2019).
ischemic stroke (1 paper, 2019). A stroke disorder caused by obstruction of blood flow to the brain, due to thrombotic (local blood clot formation) or embolic (due to a blood clot or other material traveling from another site) event. "Here, we hypothesized that neuroprotection after ischemic stroke by EPO and GRINA could be mediated by the regulation of the post-ischemic UPR and in particular by the IRE1α and PERK pathways of the UPR." (PMID 31683519, 2019).
Stroke (1 paper, 2019). Sudden impairment of blood flow to a part of the brain due to occlusion or rupture of an artery to the brain. "Stroke increased Xbp1s mRNA levels, however GRINA-deficiency revealed significantly higher Xbp1s mRNA levels than WT mice 6 h after stroke (p = 0.0043)." (PMID 31683519, 2019). "For the activation of the IRE1α branch of UPR after stroke, mRNA levels of Xbp1s and Dnajb9 were measured in GRINA-deficient and wildtype primary murine cortical cells using RT-qPCR." (PMID 31683519, 2019). "GRINA-deficiency, however, revealed significantly higher Chop mRNA levels at both 6 h (p = 0.0007) and 72 h (p = 0.0001) after stroke compared to wildtype mice." (PMID 31683519, 2019). "GRINA-deficient mice revealed higher neurological impairments (8.1 ± 0.83) compared to WT mice after stroke." (PMID 31683519, 2019). "However, it should be noted that in the early phase after stroke (6 h) EPO treatment reduced apoptosis rates in GRINA-deficient mice too." (PMID 31683519, 2019). "In addition, GRINA-deficiency increased apoptosis and the activation of the corresponding PERK arm of the UPR after stroke." (PMID 31683519, 2019). "Furthermore, GRINA might play a crucial role in the post-ischemic UPR, since GRINA-deficiency activates the PERK arm of the UPR and increases apoptosis after stroke." (PMID 31683519, 2019).
tumor (5 papers, 2018 to 2025). "Glutamate Receptor, Ionotropic, N-Methyl D-Aspartate-Associated Protein 1 (GRINA) is located at chromosome 8q24.3 and belongs to the N-Methyl D-Aspartate (NMDA) receptors which are closely associated with tumour progression according to some studies." (PMID 30541591, 2018). "GRINA expression was higher in tumour cells than in immortalized gastric mucosal epithelial cells, and was also higher in tumour tissues compared to matched normal tissues." (PMID 30541591, 2018). "The results demonstrated elevated expression of GRINA in tumour tissues consistent with the bioinformatics results." (PMID 30541591, 2018). "In CRC, miR-296-3p was found to inhibit tumor cell proliferation by suppressing GRINA expression." (PMID 37751586, 2023). "Next, we aimed to determine the role of GRINA in tumour growth in vivo." (PMID 30541591, 2018).
cancer (4 papers, 2018 to 2023). A tumor composed of atypical neoplastic, often pleomorphic cells that invade other tissues. "The expression of GRINA in cancer tissues was significantly higher than that in normal tissues." (PMID 30541591, 2018).
psychiatric diseases (1 paper, 2023). "Furthermore, upregulation of GRINA has been consistently observed in various psychiatric diseases in human subjects." (PMID 38075274, 2023).
GRINA also shares sentences with these, for which no sentence is quoted: Arthritis (1 paper); atherosclerosis (1); breast carcinoma (1); Coronary artery disease (1); epilepsy (1); glioma (1); neuroblastoma (1); osteoarthritis (1); pancreatic adenocarcinoma (1); Transient Cerebral Ischemia (1).